WLS (Wnt ligand secretion mediator)
Description:
Regulates Wnt proteins sorting and secretion in a feedback regulatory mechanism. This reciprocal interaction plays a key role in the regulation of expression, subcellular location, binding and organelle-specific association of Wnt proteins. Plays also an important role in establishment of the anterior-posterior body axis formation during development (By similarity).
Synonyms: EVI; C1orf139; GPR177; FLJ23091; MRP; mig-14; ZKS
Tractability: Small molecule: a structure with a bound ligand is known. Antibody: UniProt places it where antibodies can reach, with high confidence; its Gene Ontology location is reachable by antibodies, with high confidence; UniProt predicts a signal peptide or a membrane-spanning region. PROTAC: ubiquitination databases record sites on it; its protein half-life has been measured.
Gene: Protein-coding gene on chromosome 1 (68,098,473 to 68,233,120, reverse strand). Ensembl gene ENSG00000116729.
Subcellular location: Golgi apparatus membrane; Cytoplasmic vesicle membrane; Cell membrane; Endoplasmic reticulum membrane; Early endosome membrane
Subcellular location (Human Protein Atlas): Cytosol; Endoplasmic reticulum
Pathways (Reactome):
Signal Transduction: WNT ligand biogenesis and trafficking
Gene Ontology:
Molecular function: protein binding; Wnt-protein binding
Biological process: intracellular protein transport; positive regulation of canonical Wnt signaling pathway; positive regulation of Wnt protein secretion; positive regulation of Wnt signaling pathway; Wnt protein secretion; anterior/posterior axis specification; positive regulation of canonical NF-kappaB signal transduction; cementum mineralization; exocrine pancreas development; hindbrain development; mesoderm formation; midbrain development; Wnt signaling pathway
Cellular component: cytoplasmic vesicle; early endosome; early endosome membrane; endoplasmic reticulum; endoplasmic reticulum membrane; Golgi apparatus; Golgi membrane; plasma membrane; trans-Golgi network; endocytic vesicle membrane; endomembrane system; extracellular exosome; cytoplasmic vesicle membrane
Genetic constraint (gnomAD): Loss-of-function variants: 20 observed, 61.16 expected, observed/expected ratio (o/e) 0.33, 90% interval 0.23 to 0.47. The upper end of that interval is the gene's LOEUF score, 0.47, which puts it in group 2 of 6, group 1 being the genes least tolerant of losing a copy. Missense variants: 577 observed, 702.55 expected, observed/expected ratio (o/e) 0.82, 90% interval 0.77 to 0.88. Synonymous variants: 239 observed, 247.82 expected, observed/expected ratio (o/e) 0.96, 90% interval 0.87 to 1.07.
Homologues: Orthologues: pig WLS (98% identical), mouse Wls (96% identical), rat Wls (96% identical), guinea pig WLS (94% identical), chimpanzee WLS (93% identical), macaque WLS (93% identical), dog WLS (93% identical), rabbit WLS (92% identical), zebrafish wls (78% identical), tropical clawed frog wls (74% identical), Drosophila melanogaster wls (45% identical), Caenorhabditis elegans mig-14 (38% identical).
Diseases named in the same sentence as WLS in open-access papers:
WLS is named in the same sentence as 28 diseases in open-access papers, as found by Europe PMC text mining. Sharing a sentence is not in itself a finding about the gene and the disease. The quoted sentences say what the papers report.
breast carcinoma (2 papers, 2023 to 2024). "Initially, univariate Cox regression analysis revealed that 12 genes were associated with the prognosis of breast cancer, followed by LASSO analysis to derive a prognostic signature composed of 8 genes, including CERCAM, EMP1, SDC1, PRKG1, XG, TNN, WLS, and PDLIM4." (PMID 38728370, 2024).
osteosarcoma (2 papers, 2014 to 2016). A usually aggressive malignant bone-forming mesenchymal neoplasm, predominantly affecting adolescents and young adults. "We identified three genes located in focal gains and overexpressed in a significant fraction of both osteosarcoma sets: CD83 (6p23), RTN1 (14q23.1), and GPR177 (WLS/EVI) (1p31.3)." (PMID 25551557, 2014). "No information is available about the expression of GPr177(WLS/EVI) in osteosarcomas." (PMID 25551557, 2014).
leukemia (1 paper, 2021). A malignant (clonal) hematologic disorder, involving hematopoietic stem cells and characterized by the presence of primitive or atypical myeloid or lymphoid cells in the bone marrow and the blood. "Six genes were identified in baboons (WNT3, POU2AF1, CCR7, ARG2, CD177, and WLS) and validated in human leukemia patients exposed to radiotherapy." (PMID 33737626, 2021).
medulloblastoma (1 paper, 2025). A malignant, invasive embryonal neoplasm arising from the cerebellum. "These include enhancers of regulators of genes that drive glutamatergic neuronal identity (e.g., PAX6, WLS), and known drivers of medulloblastoma (OTX2, MYCN, CBFA2T2)." (PMID 41279093, 2025).
pancreatic cancer (1 paper, 2021). "Furthermore, we demonstrated that both Wntless homolog protein (WLS) and myristoylated alanine-rich C-kinase substrate (MARCKS) could participate in oxaliplatin resistance in pancreatic cancer cells." (PMID 33578797, 2021).
WLS also shares sentences with these, for which no sentence is quoted: tumor (7 papers); cancer (3); amyotrophic lateral sclerosis (1); breast tumor (1); colorectal cancer (1); colorectal tumors (1); Crohn disease (1); drug dependence (1); escherichia coli infection (1); gastric tumors (1); glioma (1); hematological tumors (1); hepatocellular carcinoma (1); inflammatory bowel disease (1); lung adenocarcinoma (1); Obesity (1); opioid dependence (1); osteoporosis (1); parasite infections (1); Parkinson disease (1); Pulmonary hemorrhage (1); schizophrenia (1); Testicular atrophy (1).